ANGPTL3 (angiopoietin like 3)
Diseases named in the same sentence as ANGPTL3 in open-access papers (continued):
Sharing a sentence is not in itself a finding about the gene and the disease.
Thrombocytopenia (1 paper, 2024). A reduction in the number of circulating thrombocytes. "Thrombocytopenia-associated changes common to both tumor types included an increase in RANTES, EGF, and angiopoietin-like 3 levels, and a reduction in PF4 levels." (PMID 38493157, 2024).
viral infection (1 paper, 2025). "It is worth noting that genes relating to innate immune response to viral infection (e.g., DHX58, MX1, IFITM-like), cell structure integrity (e.g., ANGPTL3, ANGPTL4, ELFN2, COL5A3) and transcription factors (e.g., TUB) remained upregulated throughout the acute phase of infection (1–6 dpi)." (PMID 40758745, 2025).
cardiovascular disease (34 papers, 2018 to 2025). "It then became clear in our human population study that loss-of-function mutations in ANGPTL3 are protective against cardiovascular disease." (PMID 37814839, 2023). "A current report declared that the crystal structure of the fibrinogen-like domains of ANGPTL3 strongly linked to cardiovascular disease." (PMID 35399079, 2022). "To test the in vivo therapeutic potential of the single-AAV ABE system, we installed in mice mutations that are associated with decreased cardiovascular disease risk in humans by precisely knocking down Pcsk9 or Angptl3 protein levels." (PMID 35902773, 2022). "The role of angiopoietin-like 3 (ANGPTL3) in blood lipid levels, cardiovascular disease risk, and glucose metabolism has received wide attention." (PMID 30683883, 2019). "Notably, among these proteins, the levels of angiopoietin-related protein 3 (ANGPTL3), a protein known to be associated with cardiovascular disease (CVD) in the general population, decreased with statin therapy." (PMID 40924496, 2025). "However, such evidence implicating angiopoietin-like protein 3 (ANGPTL3) as a target for cardiovascular disease is more limited when considering common genetic variants." (PMID 39407214, 2024). "However, the effect of pharmacologically targeting ANGPTL3 on risk factors for cardiovascular disease in specific metabolically challenged subjects remains to be elucidated in future studies." (PMID 31416197, 2019). "Thus, increased ANGPTL2 and ANGPTL3 levels in obese children and adolescents might be considered a risk factor that predisposes them to early cardiovascular disorders." (PMID 34422408, 2021). "Our findings corroborate the literature regarding the important roles of ANGPTL4, ANGPTL3, and endostatin in cardiovascular diseases." (PMID 39728292, 2024). "Therapeutic blocking antibodies and anti-sense oligonucleotides targeting ANGPTL3 reduce atherogenic lipoprotein levels and decrease the odds of developing cardiovascular disease in humans, supporting ANGPTL family of proteins as druggable targets." (PMID 36853945, 2023). "This supported the idea that if you lack ANGPTL3, you've won the genetic lottery and you are protected against cardiovascular disease." (PMID 37814839, 2023). "My initial focus was on genes like ANGPTL3 and cardiovascular disease, but my academic lab has more recently pivoted to other diseases." (PMID 37814839, 2023). "Then, the real question was, can we really prove that loss of functional ANGPTL3 not only reduces LDL cholesterol levels, but also protects against cardiovascular disease?" (PMID 37814839, 2023). "Supported by an abundance of experimental and genetic evidence, angiopoietin-like protein 3 (ANGPTL3) has emerged as a promising therapeutic target for cardiovascular disease." (PMID 34371033, 2021). "Genetic observations strongly support the utility of developing new ANGPTL3 inhibitors to reduce TG level and the incidence of cardiovascular disease." (PMID 32440963, 2020). "ANGPTL3 deficiency results in lower levels of triglycerides, LDL-cholesterol (LDL-C), and HDL-cholesterol (HDL-C), and may protect from cardiovascular disease." (PMID 41148215, 2025). "Furthermore, a novel genome editing tool is under development to permanently inactivate the ANGPTL3 gene in the liver to reduce LDL in patients with cardiovascular disease." (PMID 40503438, 2025). "In an analysis of 13,102 patients with cardiovascular disease, carriers with loss-of-function mutations in ANGPTL3 had an approximately 40% lower risk of cardiovascular disease than non-carriers." (PMID 37424875, 2023). "ANGPTL3 has been shown to play a key role in the lipoprotein system by increasing circulating levels of triglycerides and LDL-C, which are two major risk factors for cardiovascular disease." (PMID 37375802, 2023).
cardiovascular disease (continued). "For this reason, ANGPTL3 is considered an important new pharmacological target for the treatment of cardiovascular diseases (CVDs) together with more conventional lipid lowering therapies, such as statins and anti proprotein convertase subtilisin/kexin type 9 (PCSK9) monoclonal antibodies." (PMID 30011918, 2018). "Thus, the ‘biological distance’ between ANGPTL3 and cardiovascular disease may be greater than for LPL and ANGPTL4, suggesting that statistical power may also be lower, even if the relative efficacy of these drug targets might be similar in clinical practice." (PMID 39407214, 2024). "Angiopoietin-like protein 3 (ANGPTL3) plays an important role in lipid and lipoprotein trafficking and metabolism and is positively correlated with cardiovascular disease." (PMID 38276267, 2023). "This indicated that ANGPTL3, ANGPTL4, and ANGPTL8 play important role in cardiovascular disease through regulation of lipid metabolism." (PMID 32440963, 2020). "Cardiovascular outcome trials are being considered for therapeutics that silence apolipoprotein C3 (APOC3) or angiopoietin-like 3 (ANGPTL3) because of their abilities to lower triglyceride-rich lipoproteins (TRLs) and their remnants in individuals with increased cardiovascular disease (CVD) risk." (PMID 40709279, 2025).
cancer (23 papers, 2014 to 2025). A tumor composed of atypical neoplastic, often pleomorphic cells that invade other tissues. "The results showed that CHOL, KICH, KIRC, KIRP, LIHC, and SARC cancers were associated with the downregulation of ANGPTL3." (PMID 37375208, 2023). "Our results indicated that eight SNPs in ANGPTL3 were associated with the development of various types of cancer." (PMID 37375208, 2023). "Gene expression analyses indicated that lower expression levels of ANGPTL3 and C19orf80 are associated with cancer." (PMID 37375208, 2023). "Little has been documented on the link between ANGPTL3 and cancers, yet some associations have been reported." (PMID 36203122, 2022). "The number of cancer-causing high-risk SNPs was lower in ANGPTL8 (n = 4) than in ANGPTL3 (n = 7)." (PMID 37375208, 2023). "Moreover, we identified eleven high-risk nsSNPs that cause various types of cancer: seven candidates for ANGPTL3 (L57H, F295L, L309F, K329M, R332L, S348C, and G409R) and four candidates for ANGPTL8 (P23L, R85W, R138S, and E148D)." (PMID 37375208, 2023). "Finally, with the exception of ANGPTL3, the remaining genes showed significant correlations with cancer-associated fibroblasts, endothelial cells, and microenvironment score, whereas only ANGPTL6 was significantly correlated with immune score." (PMID 34685578, 2021). "Researchers have also reported that METTL3-mediated M6A modification can decrease ANGPTL3 mRNA levels and that the inhibitory effects of METTL3 silencing on cancer progression can be partially reversed by ANGPTL3 inhibition." (PMID 41312360, 2025). "We employed cis-Mendelian randomization and colocalization to evaluate the role of 5 lipid-perturbing drug targets (ANGPTL3, ANGPTL4, APOC3, CETP, and PCSK9) in risk of 5 cancers (breast, colorectal, head and neck, ovarian, and prostate)." (PMID 40511612, 2025). "For example, knockdown of ANGPTL3, the target of the lipid-lowering therapy evinacumab, has been shown to suppress proliferation, migration, and invasion in several cancer cell lines." (PMID 40511612, 2025). "The results showed that ANGPTL3 expression is significantly downregulated in all these cancers except LIHC." (PMID 37375208, 2023). "A box plot was generated for various types of cancer to show the effect of the downregulation of ANGPTL3 and C19orf80 genes more explicitly." (PMID 37375208, 2023). "Protein docking analysis showed that 23 interface residues of ANGPTL3 interact with 23 residues of cancer-suppressing ITGB3 and ITGAV proteins." (PMID 37375208, 2023). "In contrast, a lower expression of ANGPTL3 was associated with a longer survival rate of KICH, LAML, and LIHC cancer patients." (PMID 37375208, 2023). "Dysregulated expression of ANGPTL3 and ANGPTL8 was associated with poor prognosis in cancer patients." (PMID 37375208, 2023). "METTL3 limited the stability and abundance of ANGPTL3 and enhanced several key biological behaviors (proliferation, migration and invasion) of cancer cells." (PMID 37344779, 2023). "As a member of the angiopoietin-like protein family, ANGPTL3 can be involved in several disease biological processes including tumor angiogenesis, cancer cell migration and proliferation, and tumor thrombus formation." (PMID 37344779, 2023). "The protein-coding mRNA levels of the genes in various types of cancer and adjacent normal tissue were analyzed using RNA sequence data to compare the expression level of ANGPTL3 and C19orf80 in normal and tumor tissues." (PMID 37375208, 2023). "The survival analysis showed that CHOL, KIRP, and SARC patients with low expression levels of ANGPTL3 had a shorter survival time, whereas KICH, LAML, and LIHC cancer patients with low expression levels of ANGPTL3 exhibited a high survival rate." (PMID 37375208, 2023). "Previous studies have shown that ANGPTL3 expression was upregulated in several cancer cells or tissues." (PMID 35038961, 2022).
cancer (continued). "Recent studies have found that ANGPTL3 also plays a vital role in the occurrence and development of cancers." (PMID 35038961, 2022). "Little is known on the role, if any, of circulating lipid-related factors such as PCSK9, ANGPTL3 and lipoprotein (a) in cancers." (PMID 36203122, 2022). "Except for ANGPTL3, the remaining ANGPT/ANGPTL genes were significantly correlated with the stroma and microenvironment scores, cancer-associated fibroblasts, and endothelial cells." (PMID 34685578, 2021). "Angiopoietin-like 3 (ANGPTL3), which is involved in new blood vessel growth, has been reported to exhibit an abnroaml expression in many different cancers." (PMID 34484467, 2021). "In vitro and in mouse models, ANGPTL3 knockdown reduces cancer cell proliferation and growth upregulating cyclin-dependent kinase inhibitors so arresting cell-cycle at G1 phase." (PMID 29389861, 2018). "Few evidences are reported in literature about the ANGPTL3’s role in cancer growth and invasion through MAPK cascade’s activation." (PMID 29389861, 2018). "Different studies reported that ANGPTL3 activity is one of the most important factors in cancer growth and invasion, because of the MAPK signaling cascade." (PMID 29389861, 2018). "For example, ANGPTL1 can suppress SLUG to inhibit cancer cell motility, and ANGPTL3 plays an important role in cancer growth and invasion." (PMID 26056041, 2015). "We employed drug-target Mendelian randomization (MR) to systematically evaluate the effect of 5 approved or emerging lipid-perturbing drug targets for CVD (APOC3, ANGPTL3, ANGPTL4, CETP, and PCSK9) on risk of 5 cancers (breast, colorectal, head and neck, ovarian, and prostate)." (PMID 40511612, 2025). "In this observational study, lipid profiles, PCSK9, ANGPTL3, and Lp(a) levels did not change in men diagnosed with locally advanced Gleason 8 or 9 PCa compared to at‐risk but cancer‐free men." (PMID 39888285, 2025). "Seven high-risk SNPs in ANGPTL3 and four in ANGPTL8 were predicted to be involved in cancer." (PMID 37375208, 2023). "If future studies reveal that PCSK9, ANGPTL3 or Lp(a) have a role to play in cancer progression, the availability of inhibitors -for which safety data are available in humans- could permit to reposition these inhibitors in cancers." (PMID 36203122, 2022). "In the long run, ANGPTL-3 levels after HCV eradication could promote lipotoxicity-related hepatocarcinogenesis, thereby strengthening ANGPTL-3′s emerging role in cancer." (PMID 34360721, 2021). "Few articles about ANGPTL3’s role in cancer growth and invasion were reported." (PMID 32410376, 2020). "As such, the absence of changes in Lp(a), PCSK9 and ANGPTL3 levels between men with localized PCa and men at risk could depend on the investigated cancer stage." (PMID 39888285, 2025). "Importantly, the inhibitory effect of METTL3 silencing on cancer could be reversed to some extent by ANGPTL3 inhibition." (PMID 37344779, 2023). "Survival rate analysis indicated that both upregulation and downregulation of ANGPTL3 and ANGPTL8 leads to low survival rates in various types of cancer." (PMID 37375208, 2023). "We believe that the comprehensive analysis of nsSNPs in ANGPTL3 and ANGPTL8 represents a significant advancement in our understanding of these proteins and their role in cancer." (PMID 37375208, 2023). "The current study’s findings indicate that ANGPTL3 and ANGPTL8 proteins are tumor suppressors and are aberrantly expressed in various types of cancer." (PMID 37375208, 2023). "Our findings indicate that ANGPTL3 and ANGPTL8 play a pivotal role in cancer progression by interacting with tumor-suppressor proteins such as ITGB3, ITGAV, RASSF5, and FNDC5." (PMID 37375208, 2023).
cancer (continued). "The “Target” run with ANGPTL3 as a target gene shows that altered genes of various cancer types including MAPK1, CASP5, COL3A1, ITGAM and TMEM59L change the expression of ANGPTL3." (PMID 37375208, 2023). "Angiopoietin-like protein 3 (ANGPTL3) is a member of the ANGPTL family of proteins with numerous functions in lipid metabolism, inflammation, glucose homeostasis, and cancer." (PMID 35456658, 2022). "We further found that ANGPTL1, ANGPTL3, ANGPTL4, and ANGPTL8 were significantly highly expressed in HCC cell lines than other types of cancer cell lines (p < 0.05)." (PMID 35692877, 2022). "Angiopoietin-related protein 3 (ANGPTL3) is another protein involved in angiogenesis and hence cancer; however, it also has essential functions in glucose metabolism." (PMID 35126141, 2021). "It indicates that lipid profiles, PCSK9, ANGPTL3, and Lp(a) levels were not significantly altered in localized high‐grade (Gleason 8 or 9) PCa patients compared to cancer‐free men." (PMID 39888285, 2025). "However, in the future, in vivo studies should be conducted to validate the significance of the correlation of these SNPs in ANGPTL3 and ANGPTL8 with a specific type of cancer." (PMID 37375208, 2023). "The current study sought to identify high-risk, “non-synonymous, single-nucleotide polymorphisms” (nsSNPs) in both ANGPTL3 and ANGPTL8 to evaluate the role that these nsSNPs play in various types of cancer." (PMID 37375208, 2023). "Overall, the current study revealed that both ANGPTL3 and ANGPTL8 constitute potential prognostic biomarkers for cancer; moreover, nsSNPs in these proteins might lead to the progression of cancer." (PMID 37375208, 2023). "Given the mounting evidence for the role of ANGPTL-3 and ANGPTL-4 in cancer, perhaps the hepatic microenvironment shaped by advanced fibrosis in F3 HCV patients could be the one that dictates the depth of ANGPTLs’ involvement in HCC development." (PMID 34360721, 2021). "Angiopoietin-like 3 (ANGPTL3), which is involved in new blood vessel growth and stimulation of mitogen-activated protein kinase (MAPK), is expressed aberrantly in several types of human cancers." (PMID 25644496, 2015). "Nonetheless, our findings suggesting little evidence of association of genetically proxied ANGPTL3, APOC3, CETP, and PCSK9 inhibition with cancer risk may help to deprioritize further evaluation of these proteins as intervention targets for cancer prevention." (PMID 40511612, 2025).